BRCA2 (BRCA2 DNA repair associated)
Diseases named in the same sentence as BRCA2 in open-access papers (continued):
Sharing a sentence is not in itself a finding about the gene and the disease.
breast cancer (continued). "The first evidence of breast cancer risk reduction with tamoxifen in healthy BRCA1 and BRCA2 germline variant carriers came from a subgroup analysis of the P-1 trial." (PMID 37628558, 2023). "Approximately 55%-65% of individuals with BRCA1 and about 45% of females with BRCA2 will develop breast cancer by the age of 70." (PMID 37113463, 2023). "Anthropometric measures are associated with breast cancer risk for BRCA1 and BRCA2 variant carriers, with relative risk estimates that are generally consistent with those for women from the general population." (PMID 37340476, 2023). "This is the first prospective study to analyze the association of breast cancer risk with anthropometric measures by menopausal status, separately for BRCA1 and BRCA2 variant carriers." (PMID 37340476, 2023). "Hereditary breast and ovarian cancer (HBOC) is a syndrome of predisposition to cancer development, including breast cancer and ovarian cancers, caused by germline pathogenic variants of BRCA1 or BRCA2 (gBRCA1/2-positive)." (PMID 37957733, 2023). "According to The Breast Cancer Information Core (BIC), a catalog of BRCA1 and BRCA2 mutations identified worldwide, the most commonly identified BRCA1 mutations are 185delAG (16.5%), 5382insC (8.8%), and the C61G missense mutation (1.8%)." (PMID 36902416, 2023). "PALB2 is the third most important breast cancer susceptibility gene after BRCA1 and BRCA2, presenting with varying prevalence and mutational profiles in different populations." (PMID 37686625, 2023). "In this study, we successfully knocked-in the BRCA1 E255* and the BRCA2 C711* mutations into the Capan-2 and T3M4 PDAC cell lines and in the MCF7 breast cancer cell-line, using CRISPR/Cas9-mediated technology." (PMID 37907567, 2023). "The NCCN criteria for genetic testing includes any woman with breast cancer of Ashkenazi Jewish descent, due to the established frequency of pathogenic variants in BRCA1 and BRCA2 in this population." (PMID 36544278, 2023). "Results displayed that the cumulative risk of breast cancer by age 80 is 72% for BRCA1 carriers and 69% for BRCA2 carriers." (PMID 37476378, 2023). "Instead, oophorectomy has recently been suggested to reduce breast cancer recurrence and mortality of both BRCA1 and BRCA2 variant carriers." (PMID 37173335, 2023). "Based on the mutation frequencies, the magnitude of cancer risk, and the influence on clinical management with mutation carriers, the most important breast cancer susceptibility genes include BRCA1, BRCA2, PALB2, and CHEK2." (PMID 37510234, 2023). "The primary genes associated with hereditary breast cancer are BReast CAncer gene 1 (BRCA1) and BRCA2, which produce proteins involved in DNA damage repair." (PMID 37181043, 2023). "Our study depicted the mutational patterns of BRCA1, BRCA2, and PALB2 in Taiwanese breast cancer patients through tumor-only sequencing." (PMID 38098088, 2023). "In term of breast cancer subtype, BRCA1 carriers is typically associated with the TNBC subtype, and hormone receptor‐positive breast cancer is common in BRCA2 carriers." (PMID 35778884, 2023). "BRCA1 and BRCA2 are detected in at least 5% of unselected patients with breast cancer and in approximately 30% of patients with a positive family history of breast or ovarian cancer." (PMID 37644384, 2023). "Male breast cancer (MBC) is a rare disease accounting for less than 1% of all breast cancer cases and it was previously shown that nearly 90% of MBC arising in BRCA mutation carriers are found to harbor a BRCA2 mutation." (PMID 37055759, 2023). "In particular, germline mutations in genes responsible for DNA repair, such as breast cancer susceptibility genes 1 and 2 (BRCA1 and BRCA2), are found to greatly increase an individual’s risk." (PMID 36765666, 2023).
breast cancer (continued). "Approximately 10% of breast cancer cases occur in patients with germline pathogenic variants of BRCA1, BRCA2, and other DDR genes, which are correlated with an increased risk of breast, and other cancers." (PMID 37350936, 2023). "This is the first study with a large prospective component to analyze the association anthropometric measures with breast cancer risk by menopausal status for BRCA1 and BRCA2 variant carriers separately." (PMID 37340476, 2023). "Patients with newly diagnosed early-stage breast cancer who carry a PV/LPV in BRCA1 or BRCA2 are often advised to undergo mastectomy, which can be skin-sparing or nipple-sparing." (PMID 37781190, 2023). "Protein-truncating variants in BRCA2 and ATM were associated with a high risk of breast cancer, whereas PTVs in BRCA1 and PALB2 were associated with a high risk of estrogen receptor (ER)-negative disease." (PMID 37790698, 2023). "Our findings establish BRCA2 dsDNA binding activity, unique to the NTD and impaired in the breast cancer variants C315S and S273L, as essential for the ssDNA gap suppression activity of BRCA2." (PMID 36707518, 2023). "The existence of tumor-infiltrating lymphocytes in different breast cancer subtypes has been confirmed, with high frequency of infiltration of immune cells in breast cancers associated with BRCA1 and BRCA2 mutations." (PMID 37813891, 2023). "For women of the high-risk population, the cumulative risk of developing breast cancer by age 80 is 72% for BRCA1 and 69% for BRCA2 carriers." (PMID 36765786, 2023). "Distinct from liposome mediated gene delivery, in our study we used inorganic CA nano vector for delivering the BRCA1 and BRCA2 genes into three different types of breast cancer cell lines." (PMID 36631481, 2023). "This was not predictable considering some studies that showed a 15-year actuarial risk of contralateral breast cancer of 36.1% for women with P/LP variants BRCA1 and 28.5% for women with P/LP variants in BRCA2." (PMID 36971799, 2023). "Whereas, a greater rate of BRCA1/2 germline variants was reported in familial breast cancer patients from Lebanon (15.5%), and Egypt (19.8% for BRCA1 and 30.6% for BRCA2)." (PMID 37656691, 2023). "Transgene expression of BRCA1 and BRCA2 in breast cancer cell lines using the novel vector of CA NPs potentially provided new insight for breast cancer gene therapy." (PMID 36631481, 2023). "Currently, at-risk women are often identified through familial history of breast cancer, or genetic markers, such as BRCA1 or BRCA2 mutations, which cause approximately 60% of hereditary breast cancer." (PMID 37018164, 2023). "This study aimed to assess and compare the ultrasound findings and pathologic features of BRCA1 and BRCA2 breast cancers." (PMID 36905492, 2023). "The tumor suppressors breast cancer susceptibility genes BRCA1 and BRCA2 are critical to the repair of double-strand breaks in DNA via homologous recombination repair (HRR)." (PMID 37803017, 2023). "Often, high-grade breast cancer and TNBCs show somatic mutations or abnormal BRCA1/BRCA2 expression." (PMID 37761830, 2023). "In the example of BRCA2-d in breast cancers of the HMF data set, our model achieved an AUROC of 0.93 and a PR-AUC-E of 0.29." (PMID 36883553, 2023). "Within this group, only four recommendations were of tier 1 clinical evidence level (1x PIK3CA/KRAS-mutated breast cancer, 1x MET-mutated kidney cancer, 1x ALK fusion-positive NSCLC, and 1x BRCA2-mutated pancreas cancer)." (PMID 38136436, 2023). "Here, we describe the case of a BRCA1/BRCA2 double heterozygous female proband diagnosed with breast cancer." (PMID 37895014, 2023). "Approximately 5–10% of patients diagnosed with breast cancer have an inherited loss of function in one or both BRCA1 and BRCA2 genes." (PMID 37035242, 2023). "About 25% of TNBC patients carry breast cancer susceptibility genes 1 and 2 (BRCA1 and BRCA2) mutations." (PMID 37719058, 2023).
breast cancer (continued). "There was one instance of a duplication in MSH6 in a colon cancer patient, and three patients with duplications of BRCA2 c.5557 within the same family, two of which reported breast cancer." (PMID 37306523, 2023). "Inherited mutations in high penetrance breast cancer susceptibility genes such as BRCA1 and BRCA2 are associated with relatively high lifetime breast cancer risk." (PMID 37043488, 2023). "In this study, we focused on BRCA1 and BRCA2 gene delivery with a view to reduce breast cancer cell proliferation in different breast cancer cells." (PMID 36631481, 2023). "About 5% of cases of breast cancer occur because of germline mutations in BRCA1 and BRCA2 and 95% remaining depend on the genetic changes in the breast cancer susceptibility gene." (PMID 37235839, 2023). "Based on one meta-analysis, the estimated mean cumulative risk for developing breast cancer by age 70 for carriers of the BRCA1 variant is 57%, whereas the risk for carriers of the BRCA2 variant is a little lower at 49%." (PMID 37781190, 2023). "Since the discovery of the high-risk breast cancer predisposition genes BRCA1 and BRCA2, extensive efforts have tried to identify additional breast cancer predisposition genes." (PMID 36707629, 2023). "Although the somatic mutational landscape, molecular signatures, and HRDetect are well-established in unselected breast cancer, studies of these features among non-BRCA1/BRCA2 high-risk familial breast cancers are limited." (PMID 37316882, 2023). "The majority of tumors in BRCA1 mutation carriers are of the triple-negative subtype while over 70% of tumors among BRCA2 carriers are luminal-like, a similar proportion as in the general population of breast cancer patients." (PMID 38036573, 2023). "Magnetic resonance imaging (MRI) represents the most sensitive technique to detect breast cancer, and this is recommended annually in addition to mammography for screening women with an inherited BRCA1 or BRCA2 mutation." (PMID 37370892, 2023). "Mutations in BRCA1/2 are most common, causing a significantly increased risk of breast cancer of about 50–70% (BRCA1) and 40–60% (BRCA2) as well as of ovarian cancer of about 40–50% (BRCA1) and 15–25% (BRCA2) by 70–80 years of age." (PMID 37623237, 2023). "The frequency of BRCA1 and BRCA2 deletions in breast cancer is higher than the frequency of amplifications and often represents about 10–15% of cases." (PMID 37628606, 2023). "Here we examined the impact of two traditional markers of hereditary cancer risk (age at breast cancer diagnosis and family cancer history) on the risk of carrying a PV in the most commonly mutated breast cancer-risk genes: ATM, BRCA1, BRCA2, CHEK2, and PALB2." (PMID 37084156, 2023). "Germline mutations in the breast cancer susceptibility genes, BRCA1 and BRCA2, are the most common causes of hereditary breast and ovarian cancer (HBOC) syndrome." (PMID 35778884, 2023). "In patients carrying pathogenic variants, the BRCA1/2 genes show incomplete penetrance and the cumulative risk at the age of 80 years is up to 72% for breast cancer in BRCA1 P/LP variants carriers and up to 69% in BRCA2 P/LP variants carriers." (PMID 36971799, 2023). "The cumulative lifetime risk up to age 80 to develop breast cancer is 72% for BRCA1 GPV (95% CI: 65–79%) and 69% for BRCA2 GPV (95% CI: 61–77%)." (PMID 37046756, 2023). "Inherited deleterious variants in BRCA1 and BRCA2 genes are highly penetrant for HBOC, with lifetime risks (dependent upon the gene and population) up to 57% for breast cancer and up to 40% and 18% for ovarian cancer for BRCA1 and BRCA2 carriers, respectively." (PMID 36833429, 2023). "In order to identify those with a higher hereditary propensity to breast cancer, AI can analyze genetic data, such as breast cancer gene 1 (BRCA1) and BRCA2 mutations." (PMID 38192969, 2023).
breast cancer (continued). "Especially, considering that our families are selected based on a combination of multiple breast cancer cases, early onset of breast cancer, and ovarian cancer in the families, criteria that makes them very similar to the families with BRCA1/BRCA2 mutations." (PMID 37316882, 2023). "Women face an approximately 72 and 69% risk of developing breast cancer associated with BRCA1 and BRCA2 mutations, respectively, by the age of 80, compared with 12% among women in the general population." (PMID 36690978, 2023). "Treatment of MCF-7 breast cancer cells with BRCA1 + NP and BRCA2 + NP was linked with de-phosphorylation (deactivated form) of MAPK without an alteration in the total MAPK level." (PMID 36631481, 2023). "Higher young-adult BMI was associated with lower risk of premenopausal breast cancer both in BRCA1 (HR 0.75 per 5 kg/m2, 95% CI 0.66–0.84) and BRCA2 (HR 0.76 per 5 kg/m2, 95% CI 0.65–0.89) variant carriers." (PMID 37340476, 2023). "In another study, researchers reviewed 114 NSM performed from 2008 to 2019 on patients with breast cancer in 105 BRCA1/2 carriers (56 BRCA1, 47 BRCA2, and two women with both mutations)." (PMID 37781190, 2023). "A previous meta-analysis reported that the risk of breast cancer was reduced by about 50% in carriers of BRCA1 and BRCA2 mutations who underwent risk-reducing bilateral salpingo-oophorectomy (RRSO)." (PMID 37781206, 2023). "As a result, we performed mutation analysis in canine BRCA2 exon 11, which encodes the HCR and BRC repeats, from canine mammary tumor and tumor-free samples." (PMID 36851449, 2023). "Patients with germline BRCA1 and/or BRCA2 pathogenic variants and HER2-negative, high-risk early breast cancer who had received neoadjuvant or adjuvant chemotherapy and completed local treatment were eligible." (PMID 37005966, 2023). "In this review, we first summarize and update the clinical trial results of the four FDA approved PARPi in treating cancers with BRCA1 and BRCA2 (BRCA1/2) mutations, including cancers of the breast, ovary, pancreas, and prostate." (PMID 37035242, 2023). "Activation of an intrinsic interferon response has been observed in BRCA2-depleted breast cancer cells and has been attributed to endogenously arising DNA damage because these cells are defective in DNA repair." (PMID 37626143, 2023). "In Japan, 1.45% of breast cancer cases reportedly involve a BRCA1 pathogenic variant and 2.71% have some BRCA2 pathogenic variant." (PMID 37957733, 2023). "Our study here demonstrated the primary use of biodegradable CA NPs to deliver BRCA1 and BRCA2 plasmids into breast cancer cells and explored the outcome of gene augmentation on tumor regression." (PMID 36631481, 2023). "Among participants with a family history of breast cancer, PTVs in ATM, BRCA2, BRCA1, PALB2 and RAD50 were associated with an increased risk of breast cancer." (PMID 37790698, 2023). "The frequency of a variant of uncertain significance (VUS) of BRCA1/2 in breast cancer varies among different studies; a recent study reported a rate of 9% mostly in non-BRCA1- or BRCA2-carrying tumors." (PMID 37173992, 2023). "Antisense oligonucleotide mediated knockdown of BRCA2 increased the sensitivity of human lung, ovarian and breast cancer cells to cisplatin and reversed the resistance to cisplatin acquired by head and neck cancer cells." (PMID 37113717, 2023). "The notion that ER+ breast cancer in BRCA2 carriers has special prognostic properties is supported by findings of increased rate of high recurrence scores (RS) in BRCA1/2 carriers." (PMID 38036573, 2023).
breast cancer (continued). "Using BRCA2-d in the set of HMF breast cancer tumours (n = 645) as an example, we observed biallelic LOF events in 17 (2.6%; 14 germline, 3 somatic) tumours and monoallelic LOF events in 7 (1.1%; 4 germline, 3 somatic) tumours." (PMID 36883553, 2023). "Genetics also plays a pivotal role, with certain gene mutations, like Breast Cancer gene 1 & 2 (BRCA1 and BRCA2), elevating risk." (PMID 38054148, 2023). "Proportions vary with ancestry, but an estimated 5–10% of breast cancer cases carry germline variants in genes associated with moderate to strong breast cancer risk (e.g., BRCA1, BRCA2, and CHEK2)." (PMID 37060015, 2023). "Our study presents the one of the largest cohorts of breast cancer patients with BRCA1, BRCA2, and PALB2 mutations detected through tumor-only sequencing in Taiwan." (PMID 38098088, 2023). "Based on our results, in Poland, we use a panel of founder mutations in BRCA1, BRCA2, CHEK2, and PALB2 as an initial screening tool for all patients with breast cancer and unaffected individuals with a positive family history of breast cancer." (PMID 37510234, 2023). "We analyzed the overall survival of patients with tumors harboring BRCA2, RAD51C or combinations of BRCA2 + RAD51C mutations using the breast cancer genome datasets available at cBioportal.org39,40." (PMID 36906610, 2023). "The data presented here showed that the presence of familial breast cancer was more strongly associated with PV carrier status for ATM, BRCA1, BRCA2, CHEK2, and PALB2, in affected women (similar to previous studies)." (PMID 37084156, 2023). "The prevalence of PV or LPV in men with breast cancer ranges from 132%, with BRCA2 being the most common." (PMID 37232811, 2023). "We designed our study to deliver BRCA1 and BRCA2 tumor suppressors in the form of plasmid by means of inorganic Carbonate Apatite (CA) nanoparticles (NPs) carrier and evaluated breast cancer cell growth both in vitro and in vivo." (PMID 36631481, 2023). "The cumulative risk of breast cancer in carriers of variants in BRCA1 and BRCA2 genes was reported to be 72% and 69%, respectively, and women with BRCA1/2 variants are advised to undergo prophylactic risk-reducing surgery to decrease cancer-related mortality." (PMID 37656691, 2023). "On the other hand, we demonstrated, for the first time, a decrease of 40% and 55% in the circRNA/mRNA ratio for BRCA1 and BRCA2, respectively, in breast cancer tissues compared to normal adjacent tissues." (PMID 37046838, 2023). "Ovarian cancer and breast cancer are hereditary cancers, and BRCA1 and BRCA2 are well known as causative genes." (PMID 37781206, 2023). "After reviewing the medical histories of (6052) women with BRCA1 or BRCA2 mutation, half of them developed breast cancer (especially TNBC) and faced a twofold increase risk of diabetes in the 15 years after breast cancer diagnosis." (PMID 37510134, 2023). "STING activation is closely associated with DDR, and breast cancer often exhibits DDR-related gene alterations, particularly in BRCA1 or BRCA2 genes." (PMID 37448962, 2023). "Among breast cancer-mutant genes, the most common genes are Breast Cancer Susceptibility Gene 1 (BRCA1) and Breast Cancer Susceptibility Gene 2 (BRCA2) involved in DNA repair." (PMID 37476378, 2023).